PTH2 (parathyroid hormone 2)
Description:
Plays a role as a potent and selective agonist of PTH2R resulting in adenyl cyclase activation and intracellular calcium levels elevation. Induces protein kinase C beta activation, recruitment of beta-arrestin and PTH2R internalization. May inhibit cell proliferation via its action on PTH2R activation. Neuropeptide which may also have a role in spermatogenesis. May activate nociceptors and nociceptive circuits.
Synonyms: TIP39
Tractability: Small molecule: a structure with a bound ligand is known. Antibody: its Gene Ontology location is reachable by antibodies, with high confidence; UniProt places it where antibodies can reach, with medium confidence; UniProt predicts a signal peptide or a membrane-spanning region.
Gene: Protein-coding gene on chromosome 19 (49,422,419 to 49,423,660, reverse strand). Ensembl gene ENSG00000142538.
Subcellular location: Secreted
Pathways (Reactome):
Signal Transduction: Class B/2 (Secretin family receptors); G alpha (s) signalling events
Gene Ontology:
Molecular function: protein binding
Biological process: neuropeptide signaling pathway
Cellular component: extracellular region
Genetic constraint (gnomAD): Loss-of-function variants: 6 observed, 6.6 expected, observed/expected ratio (o/e) 0.91, 90% interval 0.49 to 1.69. That is too few expected variants to judge how well the gene tolerates losing a copy. Missense variants: 156 observed, 132.3 expected, observed/expected ratio (o/e) 1.18, 90% interval 1.03 to 1.35. Synonymous variants: 67 observed, 69.23 expected, observed/expected ratio (o/e) 0.97, 90% interval 0.79 to 1.19.
Homologues: Orthologues: chimpanzee PTH2 (98% identical), macaque PTH2 (96% identical), dog PTH2 (88% identical), pig PTH2 (82% identical), rat Pth2 (80% identical), mouse Pth2 (79% identical), rabbit PTH2 (77% identical), guinea pig PTH2 (75% identical), zebrafish pth2 (29% identical).
Diseases named in the same sentence as PTH2 in open-access papers:
PTH2 is named in the same sentence as 16 diseases in open-access papers, as found by Europe PMC text mining. Sharing a sentence is not in itself a finding about the gene and the disease. The quoted sentences say what the papers report.
allergic asthma (1 paper, 2025). A asthma with a basis in a pathological type I hypersensitivity reaction. "An in-depth understanding of how pTh2 cells are regulated will be crucial for developing novel therapies for pTh2-mediated allergic diseases including allergic asthma, allergic rhinitis, atopic dermatitis, eosinophilic esophagitis and food allergy." (PMID 40089475, 2025). "We anticipate that our in vitro model for generating pTh2 cells will be leveraged to strengthen our understanding of the molecular processes driving pTh2-mediated allergic asthma." (PMID 40089475, 2025). "In summary, we have generated insights into pTh2 cell biology and establish an in vitro model for investigating pTh2 cells that proves useful for discovering molecular mechanisms involved in pTh2-mediated allergic asthma." (PMID 40089475, 2025). "Due to their proallergic phenotype, pTh2 cells have become an important drug target not only in allergic asthma but also in other allergic diseases including allergic rhinitis, atopic dermatitis, eosinophilic esophagitis and food allergy." (PMID 40089475, 2025). "Therefore, it is crucial to further investigate the effects of natural HDAC inhibitors like SCFAs on pTh2 cell differentiation and whether they are suitable candidates for treating allergic asthma." (PMID 40089475, 2025).
allergic disease (1 paper, 2025). An immune response that occurs following re-exposure to an innocuous antigen, and that requires the presence of existing antibodies against that antigen. "A major obstacle to our understanding of pTh2 cell regulation is the lack of an in vitro model allowing high-throughput molecular and functional characterisation, which could potentially pave the way for developing novel therapies targeting them in allergic diseases." (PMID 40089475, 2025).
kidney cancer (1 paper, 2017). Primary or metastatic malignant neoplasm involving the kidney. "Also, five parathyroid hormone-related proteins (PTHrPs) (PTHLH, PTH, HCRT, MC2R, and PTH2) are prominent for three kidney cancers (KICH, KIRC, and KIRP)." (PMID 28676692, 2017).
lung carcinoma (1 paper, 2022). "Other genes, such as PTH2, TBR2, WNT7B, and CER1, either have similar effects shared with their homologues or have been independently reported to be associated with lung cancer at different omics levels." (PMID 35155435, 2022).
migraine (1 paper, 2025). "Notably, PTH1R and PTH2 were upregulated in female migraine groups, highlighting parathyroid hormone receptors as potential biomarkers for female migraine patients." (PMID 40297711, 2025). "PTH1R was upregulated in female migraine without aura versus female controls, while PTH2 was both upregulated between female migraine patients and female controls, as well as between female migraine without aura and controls." (PMID 40297711, 2025). "Additionally, PTH1R and PTH2, found in GSEA of the female migraine patients, emerged as significant, interacting with key therapeutic targets in migraine research like CGRP and PACAP." (PMID 40297711, 2025).
infection (1 paper, 2020). The state of being infected such as from the introduction of a foreign agent such as serum, vaccine, antigenic substance or organism. "The carnitine acetyl transferase gene pth2, an appressorium-associated gene which catalyzes the transportation of acetyl-CoA is required for rice infection by M. oryzae." (PMID 32160211, 2020).
PTH2 also shares sentences with these, for which no sentence is quoted: tumor (4 papers); allergic rhinitis (1); Ataxia (1); atopic dermatitis (1); developmental delay (1); eosinophilic esophagitis (1); food allergy (1); fungal infection (1); Hyporeflexia (1); hypothyroidism (1).